HOXA9 (homeobox A9)
Diseases named in the same sentence as HOXA9 in open-access papers (continued):
Sharing a sentence is not in itself a finding about the gene and the disease.
lung carcinoma (36 papers, 2013 to 2025). "Several studies have evaluated the diagnostic performance of HOXA9 gene promoter methylation as part of a diagnostic panel for lung cancer." (PMID 37038139, 2023). "We aimed to develop and validate methylated HOXA9 in bronchial lavage as a diagnostic biomarker of lung cancer." (PMID 34439376, 2021). "The objectives of this study were to develop and validate the use of methylated HOXA9 in bronchial lavage fluid as a diagnostic biomarker of lung cancer." (PMID 34439376, 2021). "Of these genes, HOXA9 is reported to be strongly associated with the aggressive growth of lung cancer cells." (PMID 33238593, 2020). "Hypermethylation of HOXA9 (meth-HOXA9) has been shown to be both a sensitive and specific diagnostic marker in lung cancer tissue." (PMID 33322500, 2020). "Homeobox A9 (HOXA9) expression is associated with the aggressive growth of cancer cells and poor prognosis in lung cancer." (PMID 33238593, 2020). "HOXA9 inhibits migration of lung cancer cells and its hypermethylation is associated with recurrence in non-small cell lung cancer." (PMID 28969042, 2017). "detected that HOXA9 inhibits lung cancer cells migration and its hypermethylation is closely linked with the recurrence in non‐small cell lung cancer." (PMID 28780773, 2017). "One of the most implicated genes in lung cancer through this mechanism is Homeobox A9 gene (HOXA9)." (PMID 37038139, 2023). "In this current study, we found that HOXA7 DNA methylation was correlated with higher NDI, and methylation of HOXA7, SOX17, ZFP42, HOXA9, CDO1 and TAC1was associated with advanced stage disease in lung cancer." (PMID 39107707, 2024). "Collectively, this study reveals that the methylation of 7 genes (TAC1, CDO1, HOXA9, ZFP42, SOX17, RASSF1A and SHOX2) has a big significance in the diagnosis of lung cancer and achieved a diagnostic model with high sensitivity and specificity." (PMID 38315228, 2024). "In this study, the diagnostic performance of HOXA9 gene promoter methylation, SOX2 gene and HV2 gene CNV were evaluated for detection of lung cancer." (PMID 37038139, 2023). "The HOXA9 protein is down-regulated in lung cancer and functions as a tumor progression inhibitor, making HOXA9 a potential target for anticancer drugs." (PMID 37239989, 2023). "A number of studies have demonstrated frequent promoter methylation in lung cancer cells, including short stature homeobox gene two (SHOX2), RAS association domain family 1, isoform A (RASSF1A) and homeobox A9 (HOXA9)." (PMID 36176402, 2022). "The positive detection rates of each marker in lung carcinomas ranked from high to low were 69.1% (HOXA9), 64.7% (SHOX2), 45.6% (RASSF1A), 30.9% (cytology), and 20.6% (SEPTIN9)." (PMID 36176402, 2022). "Of note, promoter 5-mC levels of CDO1 and HOXA9 were previously utilized for plasma-based disease assessment in both early and advanced lung cancers." (PMID 36461127, 2022). "For lung cancer risk prediction, univariate logistic regression analysis revealed that methylation levels of SOX17, HOXA9, CDO1, and TAC1 were significantly related to lung cancer risk." (PMID 36153611, 2022). "In conclusion, we find that methylated HOXA9 in bronchial lavage holds potential as a supplementary tool in the diagnosis of lung cancer because it has a clinically relevant sensitivity and specificity." (PMID 34439376, 2021). "Methylated HOXA9 in bronchial lavage holds potential as a supplementary tool in the diagnosis of lung cancer with a clinically relevant sensitivity and specificity." (PMID 34439376, 2021). "We conclude that methylated HOXA9 in bronchial lavage holds potential as a supplementary tool in the diagnosis of lung cancer because it has a clinically relevant sensitivity and specificity." (PMID 34439376, 2021). "HOXA9 has been shown to be dysregulated in many solid tumors, including lung cancer, and in vitro experiments have found downregulation of HOXA9 to enhance migratory potential and stimulate cell invasiveness." (PMID 34439376, 2021).
lung carcinoma (continued). "HOXA9 protein is downregulated in lung cancer tissues and plays the role of a tumor progression repressor." (PMID 33238593, 2020). "Downregulation of HOXA9 has been suggested to enhance the migratory potential of lung cancer cells and to stimulate cell invasiveness as a target of miR-196b." (PMID 33322500, 2020). "MicroRNA hsa-mir-196b influences the survival of patients at the second stage of LUAD, which regulates targets Homeobox A9 and Runx2, etc. and acts on early stage lung cancer." (PMID 32428028, 2020). "The potential of HOX gene methylation profiles was also explored for the early detection of lung cancer in plasma and sputum, as HOXA7 and HOXA9 hypermethylation are part of the signature associated with this disease." (PMID 32635388, 2020). "For lung cancer, it was shown that the methylation levels of HOXA9, KRTAP8-1, CCND1, and TULP2 have great potential for the early recognition of LUAD in the undetermined lung nodules." (PMID 31850197, 2019). "Further investigation discovered that the HOXA9 gene in lung cancer patients were significantly more hypermethylated compared with patients with benign lung diseases and the healthy group." (PMID 31850197, 2019). "Other studies including 40 pairs of primary lung cancer and normal tissues as well as 185 induced sputum specimens also found that methylation of HOXA9 in lung cancer tissues was significantly higher compared with normal tissues." (PMID 31850197, 2019). "HOXA9 has been suggested to act as a target of miR-196b by playing a central role in controlling the aggressive behavior of lung cancer cells." (PMID 28915579, 2017). "Early stage HOXA9 methylation has been identified in lung cancer and used in early detection and prognosis." (PMID 24369052, 2013). "HOXA9 is upregulated in acute lymphocytic leukemia and epigenetically silenced in lung cancers." (PMID 39329491, 2024). "They found that HOXA9 methylation is significantly higher in lung cancer cases but, in contrast to our findings HOXA9 methylation levels were higher in squamous cell carcinoma in comparison with adenocarcinoma in lung cancer tissue samples." (PMID 37038139, 2023). "We hypothesize that methylated HOXA9 in bronchial lavage fluid can serve as a valuable adjunct in the diagnosis of lung cancer." (PMID 34439376, 2021). "In addition, the methylation status of HOXA9 was considered relevant for subtyping lung cancer using liquid biopsies or for its early detection in circulating cell-free DNA." (PMID 32635388, 2020). "Four genes (HOXA9, RASSF1A, SOX17, and TAC1) were identified as the best biomarkers (all p < 0.001) and incorporated into a logistic classifier: Probability of lung cancer = ex/(1 + ex), where x = 1.69 + 1.48 × log (HOXA9) − 1.25 × log (RASSF1A) + 0.27 × log (SOX17) + 0.16 × log (TAC1)." (PMID 29796119, 2018). "Additionally, an assay in development, Lung EpiCheck®, which includes markers such as HOXA9, has demonstrated strong performance in detecting lung cancer, including early-stage disease, across European and Chinese high-risk populations, supporting its utility as a non-invasive screening tool." (PMID 40699796, 2025). "Hypermethylated HOXA9 has been suggested as a diagnostic biomarker in lung cancer, and our group has shown that hypermethylated HOXA9 is a negative prognostic biomarker in advanced lung cancer." (PMID 34439376, 2021). "In this study, we explored the significance of the DNA methylation of 7 genes including TAC1, CDO1, HOXA9, ZFP42, SOX17, RASSF1A and SHOX2 in the blood cfDNA samples in distinguishing lung cancer from benign nodules and healthy individuals." (PMID 38315228, 2024). "To this end, we compared the DNA methylation status of 7 genes including TAC1, CDO1, HOXA9, ZFP42, SOX17, RASSF1A and SHOX2 in lung cancer cases with different stages." (PMID 38315228, 2024). "Then, we explored the diagnosis value of the DNA methylation status of 7 genes including TAC1, CDO1, HOXA9, ZFP42, SOX17, RASSF1A and SHOX2 in lung cancer." (PMID 38315228, 2024).
lung carcinoma (continued). "Here, we explored the significance of the DNA methylation of 7 genes including TAC1, CDO1, HOXA9, ZFP42, SOX17, RASSF1A and SHOX2 in the blood cfDNA samples in distinguishing lung cancer from benign nodules and healthy individuals." (PMID 38315228, 2024). "Here, we compared the DNA methylation status of 7 genes including TAC1, CDO1, HOXA9, ZFP42, SOX17, RASSF1A and SHOX2 in lung cancer cases with I–IV stages." (PMID 38315228, 2024). "NRP1 regulation of radioresistance in lung cancer involves downstream homeobox genes HOXA6 and HOXA9, and microRNA-9 is able to restore radio-sensitivity in radioresistant lung cancer cells by targeting NRP1." (PMID 37894289, 2023). "Promoter methylation of eight lung cancer-specific genes (CDO1, TAC1, SOX17, HOXA7, HOXA9, GATA4, GATA5, and PAX5) was detected using nanoparticle-based DNA extraction (MOB) followed by qMSP." (PMID 32138766, 2020). "An epigenetic classifier including four genes (HOXA9, RASSF1A, SOX17, and TAC1) that was evaluated in sputum by ddPCR reached an AUROC of 0.92 for lung cancer detection." (PMID 31817025, 2019). "While many biomarkers have been shown to be viable for gastric and urinary cancers such as bladder and CRC, one study also reported a successful DNA methylation analysis (1.7) of a panel (CDO1, TAC1, HOXA7, HOXA9, SOX17, and ZFP42 promoters) to diagnose lung cancer." (PMID 40141826, 2025). "Moreover, we compared the DNA methylation status of 7 genes (TAC1, CDO1, HOXA9, ZFP42, SOX17, RASSF1A and SHOX2) in lung cancer cases from the mass and GGNs groups." (PMID 38315228, 2024). "Following a large literature review, we explored the performance of the DNA methylation of 7 genes including TAC1, CDO1, HOXA9, ZFP42, SOX17, RASSF1A and SHOX2 in the blood cfDNA samples in distinguishing lung cancer from benign nodules and healthy individuals." (PMID 38315228, 2024). "Moreover, the methylation level of 4 genes including HOXA9 were assessed using quantitative MSP in lung cancer tissue samples, plasma samples from primarily lung cancer patients and benign lung lesions." (PMID 37038139, 2023). "In conclusion, we found that the aberrant promotor methylation of OncoMe (SHOX2, RASSF1A, SEPTIN9 and HOXA9) is a cancer-specific alteration and may be a valuable marker to aid in the differentiation of MPE, even not limited to lung cancer." (PMID 36176402, 2022). "For instance, methylation levels of APC, HOXA9, RARβ2 and RASSF1A could assist in better defining lung cancer subtypes (SCLC vs. NSCLC) and stage to develop corresponding treatment plans." (PMID 35205708, 2022). "Since the larger fraction of lung cancer patients is KRAS wild type, it is likely that methylated HOXA9 can be found in lung cancer patients irrespective of KRAS status." (PMID 33322500, 2020). "In addition to HOXA9, the methylation of HOXB4, HOXD8, and HOXD9 were also different between tumor and adjacent normal tissues in lung cancer." (PMID 31850197, 2019). "Reverse transcriptase-polymerase chain reaction (RT-PCR) showed that HOXA7 and HOXA9 mRNAs were significantly overexpressed in esophageal squamous cell carcinoma tissues compared to non-cancerous surrounding tissues, while HOXA9 was epigenetically downregulated in lung cancer." (PMID 32296636, 2020). "Six DMRs located on HOXA9, HOXD3, PCDH17, NID2, NPTX2, and SFRP2 genes exhibiting clinical accuracy over 75% irrespective of lung cancer subtype and cancer progression stages were selected as lung cancer-specific exosome DNA methylation biomarkers." (PMID 39123492, 2024). "The methylation levels of eight genes (CALCA, HOXA9, RASSF1A, CDKN2A, DLEC1, CDH13, PITX2, and WT1) in ctDNA were significantly higher in lung cancer patients than in non-lung cancer patients." (PMID 31752198, 2019).
myeloid leukemia (26 papers, 2011 to 2026). A clonal proliferation of myeloid cells and their precursors in the bone marrow, peripheral blood, and spleen. "Here we used the oncofusion gene NUP98/HOXA9 (NH9) as a deregulated HOX myeloid leukaemia model to investigate the effects of Trib2 deficiency in leukaemia cells." (PMID 29670085, 2018). "We show that enforced expression of one such gene, Hoxa9, a proto-oncogene associated with myeloid leukemia, partially reproduces the phenotype produced by E2A-PBX1 itself." (PMID 26098938, 2015). "In addition, Hoxa9 and Mzf1 involved in development of myeloid leukemia were up-regulated, while genes associated with differentiation, including Pax5 and Sox4, were down-regulated in both DKI and Dnmt3aR878H/+ groups." (PMID 31703632, 2019). "In myeloid leukemia, hnRNP Q upregulates mRNA targets, including the critical genes Myc, Hoxa9, and Ikzf2, and promotes the stem cell program." (PMID 38976670, 2024). "The expression level of HOXA9 was measured in myeloid leukaemia after treatment with chemotherapeutic drugs, including Pinometostat and Azacitidine." (PMID 35054365, 2022). "We used myeloid leukemias induced by the coexpression of Hoxa9 and Meis1 (Hoxa9/Meis1) as controls, since these genes recapitulate the disease while bypassing the upstream alterations that induce their overexpression." (PMID 32343715, 2020). "We previously showed that ectopic Trib2 expression cooperates with Homeobox transcription factor Hoxa9 to accelerate myeloid leukaemia development in mice." (PMID 29670085, 2018). "Because a translocation between MSI2 and HOXA9 had been reported to occur in bcCML patients, we focused on testing whether this translocation could be an oncogene in myeloid leukemia." (PMID 41498402, 2026). "Moreover, the protein complex formed by HOXA9 and C/EBPα targeted Cdkn2a/b to overcome G1 phase blockage, promoted the proliferation of bone marrow cells and advanced the process of myeloid leukemia." (PMID 38605318, 2024). "HOXA9 is among the biomarkers studied in the myeloid leukaemia clinical trial NCT03701295." (PMID 35054365, 2022). "In addition, miR-126 acting as an oncogene, which was found to downregulate HOXA9/PLK, was often upregulated in myeloid leukaemia and associated with poor prognosis." (PMID 26351404, 2015). "However, HOXA9 regarded as the “switch” of cell proliferation in the process of myeloid leukemia, which can promote the expression of CDK6, CyclinD1 gene and telomerase RNA by triggering pleiotropic oncogenes Myc and Myb, and provide necessary cofactors to maintain the rapid proliferation of cells." (PMID 38605318, 2024). "Recent studies have shown the activation of HOXA9 and HOXA7 via proviral integration in a mouse model of myeloid leukemia." (PMID 38944027, 2025). "Because a translocation between MSI2 and HOXA9 had been reported to occur in blast crisis CML patients, we focused on testing whether this translocation could be an oncogene in myeloid leukemia." (PMID 38234720, 2023). "Interestingly, the oncogene in ML23 are known to relate with myeloid leukemia, however, ML21 CLL-like oncogenic analysis revealed Runx1, Evi1, Glis2, and Hoxa9." (PMID 33602907, 2021). "For instance, targeting EZH2 could deplete HOXA9 and Meis1 levels in THP1 cells and disrupt the biological synergy between the two genes in inducing myeloid leukemia." (PMID 25944687, 2015).
glioma (23 papers, 2011 to 2024). A benign or malignant brain and spinal cord tumor that arises from glial cells (astrocytes, oligodendrocytes, ependymal cells). "Further, robust association of the expression of HOTAIR with the levels of homeobox protein HOXA9 was observed in glioma tissues, particularly from clinical subjects of higher-grade gliomas." (PMID 38366205, 2024). "In glioma, miR-638, miR-647 as tumor suppressors regulate cellular malignancy of gliomas by targeting HOXA9." (PMID 36376832, 2022). "Their results shown that both lncRNA HOTAIR and HOXA9 were co-expressed in gliomas with high-grade, and further HOXA9 binds directly to the promoter of HOTAIR." (PMID 36376832, 2022). "Some studies have reported that suppressed GATA4 and HOXA9 expression can inhibit malignancy and metastasis in glioma." (PMID 33503296, 2021). "We inhibited the expression of BMPER, CXCL10, and HOXA9 using siRNA in the 2 cases of glioma stem cell spheres." (PMID 32432046, 2020). "Other studies also showed that CXCL10 and HOXA9 expression levels were elevated in some glioma tissues." (PMID 32432046, 2020). "Another gene expression analysis revealed that HOTAIR was overexpressed in high-grade gliomas and it was likely controlled by DNA methylation along with the coexpression of Hoxa9." (PMID 33402862, 2020). "To verify if the frequent co-expression of HOTAIR and HOXA9 in glioma cell lines is present in glioma clinical specimens, we evaluated their expression levels and potential correlations in the Portuguese, French, and TCGA datasets." (PMID 29644006, 2018). "To test this, we studied the expression pattern of HOTAIR and HOXA9 in adult and pediatric glioma-derived cell lines by semi-quantitative reverse transcription-PCR (RT-PCR) and qPCR, and found these genes to be frequently co-expressed in glioma." (PMID 29644006, 2018). "Further analysis in 4 independent datasets showed a statistically significant correlation between the expression of HOTAIR and HOXA9 in all glioma sets." (PMID 29644006, 2018). "Previous studies found that HOXA9 in human gliomas promoted cell proliferation, and inhibited the apoptosis by suppressing PI3K-AKT pathway, which contributed to the development of tumors." (PMID 29383189, 2017). "HOXA9 expression was analyzed in WHO grades II/III glioma patients and grade IV GBM patients deposited in TCGA." (PMID 25762636, 2015). "In order to explore the role of the 5′ HOXA genes in gliomas, we first measured the expression of HOXA9, HOXA10, HOXA11, and HOXA13 protein in 66 gliomas specimens of different grades." (PMID 26356815, 2015). "The upregulation of HOXA9, HOXC6, HOXC11, HOXD1, and HOXD8 expression is associated with the proliferation and growth of glioma." (PMID 26565624, 2015). "Together, these data implicate HOXA9 as a critical molecule in the malignant progression of gliomas, and validate its prognostic value in high-grade GBM patients." (PMID 25762636, 2015). "Recently, it has been reported that HOXA9 decreases apoptosis and increases cell proliferation in glioma cells by epigenetic control and the expression of HOXA10 in GBM-derived spheres." (PMID 21600039, 2011). "Since HOXA9 and HOXA10 have been associated with temozolomide resistance in pediatric glioma, we hypothesized that MLL proteins might also have a functional role in pediatric glioma." (PMID 34381018, 2021). "Nevertheless, it is noteworthy that miR-647, miR-767-3p, and miR-935 reportedly suppress the progression of glioma through multiple regulatory axes, including miR-647/HOXA9, miR-935/FZD6, miR-935/HIF1 α, or miR-767-3p itself, making them promising biomarkers and therapeutic targets for glioma." (PMID 34434651, 2021). "ROC curve analysis indicated that the scanning parameters rCBV, rCBF, Ktrans, and Vp of the DSC-MRI and DCE-MRI can be used as imaging markers to predict the expression statuses of BMPER, CXCL10, and HOXA9 in tumor tissue, which can guide the antiangiogenic treatment of primary high-grade gliomas." (PMID 32432046, 2020).